SNORA32 (small nucleolar RNA, H/ACA box 32)
Synonyms: ACA32
Gene: Small nucleolar RNA gene on chromosome 11 (93,730,979 to 93,731,099, reverse strand). Ensembl gene ENSG00000206799.
Gene Ontology:
Biological process: RNA processing
Cellular component: nucleolus
Homologues: Orthologues: chimpanzee SNORA32 (100% identical), rat LOC120095737 (86% identical), rat Snora32 (77% identical), rat LOC120097588 (72% identical), rat LOC120102640 (57% identical), rat LOC120100386 (50% identical), rat LOC120098685 (47% identical).